TNF (tumor necrosis factor)
Diseases named in the same sentence as TNF in open-access papers (continued):
Sharing a sentence is not in itself a finding about the gene and the disease.
infection (continued). "The type I IFN pathway has been suggested to mediate the most immediate TLR responses to infection, followed by MyD88 signaling inducing expression of pro-inflammatory cytokines like TNFα." (PMID 19656404, 2009). "Tumor necrosis factor (TNF)-α is another prototypical pro-inflammatory cytokine that is induced in concert with IL-1β in response to infection, injury, and immunological challenge." (PMID 19325908, 2009). "In the vaccination model used here, however, there is a significant dampening of the infection-induced increase in IL-1β, TNF, IL-6 and iNOS, especially observable at peak parasitaemia." (PMID 19341445, 2009). "Mice treated with vancomycin but not colonized with VRE had modestly but statistically significantly higher plasma TNF-α and IL-10 levels 6 hours after the start of the infection." (PMID 19710930, 2009). "Remarkably, while treatment with NTHi lysate acutely induces 8-fold more IL-6 and almost 40-fold more TNF than infection alone, the treated mice actually have lower levels of inflammatory cytokines in their lungs by day 3 after the infection." (PMID 19137067, 2009). "Infection with this pathogen leads to a large increase in apoptotic cells in murine oviducts, but treatment with anti–TNF-α antibodies leads to a significant decrease in the level of apoptosis in the upper genital tract." (PMID 19412525, 2009). "To confirm these latency properties for wild-type HIV-1, we set up a single cycle infection assay and analyzed proviral activity upon TNFα addition." (PMID 18439275, 2008). "T lymphocytes produce TNFα after infection with influenza virus, and B lymphocytes produce TNFα after stimulation of the B cell antigen receptor and CD40." (PMID 19002259, 2008). "Macroscopic pathology of the lungs in TNF−/− mice was characterized by the presence of large nodular lesions on the pleura at 4 weeks post-infection which augmented in size and became confluent at 8 weeks post-infection." (PMID 18544042, 2008). "For instance, it is possible that TNFα addition has other stimulatory effects on the infection process, e.g. reverse transcription or integration rather than on reducing latency." (PMID 18439275, 2008). "Tumor necrosis factor alpha (TNF-alpha) plays an important role in the host defense against infection." (PMID 18662412, 2008). "On day 42 post-infection, the remaining 11 mice were dosed with either anti-TNF-α (n = 6), or control mAb (AFRC Mac 49) (n = 5)." (PMID 18823549, 2008). "A similar protective role in the innate response to infection has been demonstrated for TNF-α in B. pseudomallei infection." (PMID 18823549, 2008). "We further observed that, although the relative anti-MV potencies of TNF and type I IFN varied between individual infections, TNF in combination with either IFN-β or IFN-αA uniformly restricted MV replication in all primary human cells tested (data not shown)." (PMID 18617992, 2008). "This was associated with reduced anti-parasitic CD4+ T cell activation in the spleen and lowered hepatic IFNγ, TNF and nitric oxide production by 14 days post infection." (PMID 18802456, 2008). "Despite this more indirect analysis, TNFα increased the percentage of virus-producing cells 2 to 3 fold in infections with wild-type HIV-1 (LAI isolate) in SupT1 and Jurkat cells." (PMID 18439275, 2008). "One such signal is Tumor Necrosis Factor (TNF), which is both necessary to fight local infections of many organisms and sufficient to induce lethal septic shock if released systemically." (PMID 18654628, 2008). "Due to its modulatory effect on the immune system, infections are a predictable potential complication of anti-TNF therapy and patients are closely monitored." (PMID 19046446, 2008). "IL-6 and TNF-α are proinflammatory cytokines that regulate innate immunity physiologic host defense processes during infection, airway damage in COPD, and acute lung injury." (PMID 19057703, 2008).
infection (continued). "Conjunctival TNF-α mRNA levels have also been found to be positively correlated with duration of infection." (PMID 18974840, 2008). "These genes include eiger, a homolog of the mammalian TNF gene, and a previously uncharacterized gene called edin (elevated during infection)." (PMID 18654628, 2008). "In order to increase the luciferase signal, infection of Jurkat cells were also conducted in the presence of the LTR activating agent TNF-α." (PMID 19032754, 2008). "In LPS-stimulated whole blood, a significant reduction was observed on IL-1β and TNF-α production in the TB group, representing a reduced capacity of immune cells to react to an infection ex vivo." (PMID 19018259, 2008). "Progressive infection was paralleled by continual lowering of body weight ratios and mortality in TNF−/− mice." (PMID 18544042, 2008). "TNF-α is a proinflammatory cytokine which plays animportant role in the immune response to infections and cancer and in theregulation of inflammation." (PMID 18604304, 2008). "Elevated levels of TNF-α and IL-6 were observed on day 3 post-infection, and rose dramatically along with IFN-γ and IL-12 on day 5, coincident with the increase in bacterial load in the spleen." (PMID 18483548, 2008). "Physiologically, TNFα stimulates the recruitment of leukocytes to sites of infection and/or inflammation and also promotes their activation." (PMID 18498628, 2008). "Macrophages are also major producers of TNF-α and this cytokine is also commonly expressed during infections." (PMID 18700003, 2008). "At 72 h after infection TNFα levels remained lower in MyD88 KO mice, while MCP-1 and IL-6 levels tended to be higher in these animals." (PMID 18946505, 2008). "Functional Tlr4 also results in a higher TNF-α response after infection, and after wP vaccination and challenge." (PMID 18498620, 2008). "An enhanced expression of calcineurin able to activate the transcriptional factor NFAT to regulate IL-2 and TNFα production and the increase in local mast and goblet cells would point to an improved state of mucosal surveillance at sites of infection." (PMID 17825099, 2007). "A plot of the cumulative incidence of serious infections while receiving treatment showed that at any given point in time, it was more likely that patients in the anti-TNFα cohorts had a serious infection compared with patients in the comparison cohort." (PMID 17763441, 2007). "In this observational study, the treating rheumatologist was aware of the patient's therapy at the time of infection, possibly leading to a lower threshold for admission into the anti-TNFα cohort." (PMID 17763441, 2007). "To investigate the impact on cytokine response to infection by C. neoformans, we measured a major Th1 cytokine, TNFα." (PMID 18159253, 2007). "The crude rates of serious infection in this analysis ranged from 54.7 to 67.7 per 1,000 person-years for the 3 anti-TNFα drugs." (PMID 17763441, 2007). "Dox was removed at several times after the onset of the autoimmune process (infection with LCMV) to induce β-cell specific TNFα expression." (PMID 23675028, 2007). "Using this model, the rates of serious infection for the 3 anti-TNFα drugs were 61.7 per 1,000 person-years for etanercept, 68.9 per 1,000 person-years for infliximab, and 54.2 per 1,000 person-years for adalimumab." (PMID 17763441, 2007). "If infection with Mtb occurs after treatment is initiated, chances of developing active infection are very high if we assume reasonable levels of drug penetration into lungs (TNF bioavailability <50%)." (PMID 17953477, 2007). "We investigate the importance of specific TNF-dependent mechanisms that allow for infection control via sensitivity and uncertainty analyses." (PMID 17953477, 2007). "The model predicts that macrophages are the main producers of TNF during the early phase of infection, and that once latency is achieved lymphocytes and macrophages produce similar amounts of TNF." (PMID 17953477, 2007).
infection (continued). "On the other hand, we proposed that the prominent production of IL-10 from the early stages of the experimental HPAI infection was the compensatory response to overproduction of proinflammatory cytokines such as TNF-α, IL-6 and IL-12." (PMID 17662125, 2007). "This clearly demonstrated, in a mouse model, that there are differences between the two TNF neutralizing drugs depending on the phase of infection." (PMID 17953477, 2007). "It is possible that the secretion of IL-1β, IL-6, IL-10, and TNFα in the choriodecidua region after infection with Escherichia coli would favor their trans-membranal translocation to the amnion and thereby exert their effect on the whole membrane." (PMID 18078521, 2007). "Transcripts encoding the proinflammatory cytokines IL-1β, IL-6, IL-8, and tumor necrosis factor (TNF)-α were markedly increased in late-stage animals (average fold increase at day 5 after infection: IL-1β, 3.9; IL-6, 4.3; IL-8, 11.3; and TNF-α, 5.2)." (PMID 17725815, 2007). "We found that the immune response assessed by cellular counts, TNFα cytokine production, and fungal burden in lungs and bronchoalveolar lavage fluids during early stages of infection were equivalent." (PMID 18159253, 2007). "Both cohorts, but particularly the anti-TNFα group, were screened before initiation of treatment, to avoid inclusion of patients who had an imminent serious infection." (PMID 17763441, 2007). "There were 1,089 serious infections in total: 114 in the comparison cohort and 975 in the anti-TNFα cohort, 737 occurring while the patients were receiving therapy." (PMID 17763441, 2007). "We predict that >2% of total TNF needs to be released in soluble form to control acute infection and maintain latency." (PMID 17953477, 2007). "We describe results in these different areas of TNF study: mathematical modeling of typical infection progressions in humans, mechanisms driving infection outcomes, and anti-TNF therapies." (PMID 17953477, 2007). "This study examined the influence of different approaches on the analysis of serious infection rates following anti-TNFα therapy in patients with RA." (PMID 17763441, 2007). "Rather, macrophages are thought to play a protective role during this phase of infection – clearing trypanosomes by phagocytosis and/or by secreting TNF-α and nitric oxide (NO), which are trypanolytic and trypanostatic." (PMID 17944830, 2007). "In contrast, pre-infection with the eae mutant prevented IκB phosphorylation and thus degradation in response to TNFα treatment." (PMID 17388785, 2007). "We detected an increase not only in TNF-α but also in the downstream transcriptional response that is regulated by TNF-α and NF-κB, providing evidence that the circulating cells are responding to the large amounts of TNF-α that are induced during infection." (PMID 17725815, 2007). "TNF-alpha playsan important role in initiating and coordinating the cellularevents that make up the immune system's response to infection." (PMID 17497030, 2007). "The overall characteristics of infection, including plasma TNF levels and histopathological changes in brain, liver and lungs in mice have been described elsewhere." (PMID 17506896, 2007). "We assayed cytokine levels in BALF five hours post-infection, and observed greatly elevated TNF-α (21.4 times, p < 0.001) in RSV infected neonates." (PMID 16893457, 2006). "Compared to uninfected controls, H37Rv infection induced seven fold increases in TNF-α levels in two patients tested." (PMID 16504020, 2006). "Tumor Necrosis Factor (TNF) is a pleiotropic cytokine expressed by many cell types in response to infection or injury." (PMID 17205112, 2006). "Another type III secretion protein, SptP from S. typhimurium, is also involved in host modulation involving the MAPK pathway by inhibiting Raf activation, which ultimately attenuates the secretion of TNF from infection-activated macrophages." (PMID 16518473, 2006).
infection (continued). "A dose dependent infection was observed with VSV-G pseudotyped HIV-1 whose replication is increased by TNF-α." (PMID 16796744, 2006). "Expression of TNFα is known to be induced in intestinal lymph of genetically resistant Romney sheep during primary infection of naïve animals with T. colubriformis." (PMID 16515715, 2006). "As noted some years ago, the need for sufficient TNF to allow immune activation to proceed normally during infections is plausibly why this potentially lethal mediator has survived 300–500 million years of evolution." (PMID 17029647, 2006). "More importantly, specific blockade of soluble TNF would be predicted to abolish the detrimental pro-fibrotic effects of TNF, while maintaining sufficient host defense against infections." (PMID 17205112, 2006). "IFNγ, TNFα, and other pro-inflammatory mediators produced by these cells when responding to obligate intracellular infections are known to activate macrophages, which inhibit growth of both R. rickettsii and E. chaffeensis." (PMID 16859547, 2006). "On the one hand, TNF-α is essential for the host in tissue repair and in protective immune responses against infection." (PMID 16581537, 2006). "A 23 kDa protein, which is upregulated during intracellular infection from the intracellular pathogen Francisella tularensis, inhibits TNF secretion from the murine macrophage like cell line J774A.1 by blocking the degradation of IκB and inhibiting NF-κB." (PMID 16518473, 2006). "While TNF-KO mice succumbed to infection within 4–5 weeks, mem-TNF mice recruited normally T cells and macrophages, developed mature granuloma in the lung and controlled acute Mtb infection." (PMID 16285886, 2005). "Long-term infection control, however, with chronic inflammation disrupting TNF mediated cell-cell signalling, requires additionally soluble TNF." (PMID 16285886, 2005). "The cytokines secreted by phagocytes in response to infection include tumor necrosis factor (TNF)-α, IL-1β, IL-6, IL-8 as well as IL-10." (PMID 16280065, 2005). "Neutralisation of TNF by antibodies, which likely affects also membrane TNF, leads to the disruption of established granulomas and uncontrolled infection." (PMID 16285886, 2005). "Long-term infection control with chronic inflammation likely disrupting TNF mediated cell-cell signalling, additionally requires soluble TNF." (PMID 16285886, 2005). "The cytokines secreted by phagocytes in response to infection include TNF-α, IL-1β, IL-6, IL-8 and IL-10." (PMID 16280065, 2005). "While mem-TNF mice appeared healthy over four months, they started to loose body weight and succumbed to infection between 130 – 170 days." (PMID 16285886, 2005). "Bone marrow cell reconstitution, but not lymphocyte transfer from mem-TNF mice confer resistance to infection in TNF-KO mice." (PMID 16285886, 2005). "In acute P. aeruginosa pneumonia, increased DAFC can be related to either Pseudomonas exoproducts or to a TNF-α dependent mechanism during the first 24 hours of the infection." (PMID 15707485, 2005). "Numerous studies show that TNFα rises rapidly following acute trauma/inflammation/infection and that blocking TNFα activity reduces injury." (PMID 15987519, 2005). "Transfer of bone marrow cells, but not of lymphocytes from mem-TNF and WT mice was able to confer resistance to infection in TNF KO mice." (PMID 16285886, 2005). "TNF-α is a multifunctional cytokine that is secreted in response to injury, inflammation or infection." (PMID 16168063, 2005). "Lungs of TNF-KO mice displayed large nodular and confluent lesions on the pleura at 30 days post infection, which were much smaller and more discrete in mem-TNF mice, comparable to those in WT mice." (PMID 16285886, 2005). "A variety of host inflammatory mediators and substances such as, cytokines (TNF-α) and growth factors are released during infection and inflammation." (PMID 15588319, 2004).
infection (continued). "Topical ketorolac is very effective in neutralizing uveitis generated by experimental infection with monoclonal TNF or bacterial endotoxins." (PMID 15298714, 2004). "The proinflammatory cytokines TNF-α and IL-1β are significantly increased in susceptible BALB/c mice at 6 and 12 hours after CB3 infection, during the innate immune response." (PMID 15550215, 2004). "Infection of HT-29 cells with rAd.IκBα increased IκBα expression (lanes 7 and 8) and gave a partial inhibition of NF-κB activity induced by TNF-α (compare lane 8 with lane 6)." (PMID 14520472, 2003). "Our findings suggest that in TBM patients, after anearly activation of immune cells, there is an enhanced andcontinuous production of TNFα at the site of infection." (PMID 18472925, 1994). "In human orthotopic liver transplantation (LTX) intraoperative elevations of TNF-α (> 100 pg/ml) and IL-6 (>800 pg/ml) have been found to correlate with early post-operative rejections and infections respectively." (PMID 18475538, 1993). "Indeed, the abundance of Enterobacteriaceae or Escherichia-Shigella was positively correlated with rectal temperature at 12 and 24 h post-infection, serum TNF-α level, and jejunal IL-1β, IL-10, and TNF-α mRNA levels." (PMID 41547922, 2026). "Meanwhile, KEGG enrichment analysis indicated significant enrichment of the DE mRNAs and miRNAs in signaling pathways associated with macrophage immune activation, including the TNF, HIF-1, and MAPK signaling pathways, as well as those involved in responses to Salmonella infection." (PMID 42158325, 2026). "During infection, pro-inflammatory cytokines (e.g., TNF-α, IL-6) are upregulated." (PMID 41602759, 2026). "Bioinformatics analysis showed significant upregulation of nucleic acid-sensing receptors, interferon-stimulating factors, inflammatory mediators, and cytokines during early infection, mediated primarily through type I interferon signaling, TNF signaling, and cytosolic DNA-sensing pathways." (PMID 41594433, 2026). "Besides, the abundance of Muribaculaceae was negatively correlated with rectal temperature at 24 h post-infection and jejunal TNF-α mRNA level." (PMID 41547922, 2026). "In the current study, Spearman correlation analysis shows that the abundance of Proteobacteria exhibited a positive correlation with rectal temperature at both 12 and 24 h post-infection, as well as with serum TNF-α levels and jejunal IL-1β and TNF-α mRNA levels." (PMID 41547922, 2026). "Additionally, we observe elevated levels of specific cytokines, including IL-17, IL-6, IL-1β, and TNF-α, which collectively contribute to inflammation and tissue damage in the lungs during infection." (PMID 41597746, 2026). "Canonical discriminant analyses (CDA) indicated that IP-10, IL-4, IL-17, and TNF could be useful biomarkers for infection status." (PMID 41822517, 2026). "However, on day 7 post-infection, levels of the pro-inflammatory cytokines TNF-α, IL-6, and IL-17A significantly decreased." (PMID 41236498, 2026). "However, in piglets, infection elicited substantial increases in serum inflammatory cytokines (TNF-α, IFN-γ, IL-6, and IL-10) but produced only mild clinical signs and limited pulmonary inflammation." (PMID 41971018, 2026). "Consequently, a type I interferon along with pro-inflammatory cytokines (IL-6 and TNF-α) that are produced to suppress viral replication and recruit immune cells to the infection." (PMID 41602762, 2026). "Three days after cell-isolation from young and old animals, P. gingivalis-infection induced a significant, however, diet- and age-independent, increase in pro-inflammatory tumor necrosis factor alpha (TNFα)- and decrease in anti-inflammatory interleukin-1 receptor antagonist (IL1ra)-secretion." (PMID 40581654, 2025). "Total CD68 and CD14 prevalence increased over time after infection in RF-Bcl6no/lo tissues only, suggesting that macrophage accumulation and prolonged inflammation could contribute to sustained TNF-driven immune regulation." (PMID 40924502, 2025).